GGACT (gamma-glutamylamine cyclotransferase)
Description:
Contributes to degradation of proteins cross-linked by transglutaminases by degrading the cross-link between a lysine and a glutamic acid residue. Catalyzes the formation of 5-oxo-L-proline from L-gamma-glutamyl-L-epsilon-lysine. Inactive with L-gamma-glutamyl-alpha-amino acid substrates such as L-gamma-glutamyl-L-alpha-cysteine and L-gamma-glutamyl-L-alpha-alanine.
Synonyms: A2LD1
Tractability: Small molecule: a structure with a bound ligand is known.
Gene: Protein-coding gene on chromosome 13 (100,528,034 to 100,589,528, reverse strand). Ensembl gene ENSG00000134864.
Gene Ontology:
Molecular function: gamma-glutamylaminecyclotransferase activity; protein binding
Biological process: modified amino acid catabolic process
Cellular component: extracellular exosome; cytosol
Genetic constraint (gnomAD): Loss-of-function variants: 0 observed, 2.84 expected, observed/expected ratio (o/e) 0, 90% interval 0 to 1.03. That is too few expected variants to judge how well the gene tolerates losing a copy. Missense variants: 241 observed, 227.09 expected, observed/expected ratio (o/e) 1.06, 90% interval 0.95 to 1.18. Synonymous variants: 118 observed, 110.2 expected, observed/expected ratio (o/e) 1.07, 90% interval 0.92 to 1.25.
Homologues: Orthologues: chimpanzee GGACT (99% identical), macaque GGACT (93% identical), guinea pig GGACT (69% identical), mouse Ggact (68% identical), rat Ggact (67% identical), dog GGACT (67% identical), tropical clawed frog ggact (51% identical), zebrafish ggact.2 (50% identical), zebrafish ggact.3 (48% identical), zebrafish ggact.1 (44% identical), Drosophila melanogaster CG2811 (38% identical), Caenorhabditis elegans F42A10.9 (36% identical), and 1 more.
Diseases named in the same sentence as GGACT in open-access papers:
GGACT is named in the same sentence as 1 disease in open-access papers, as found by Europe PMC text mining. Sharing a sentence is not in itself a finding about the gene and the disease. The quoted sentences say what the papers report.
tumor (1 paper, 2023). "In particular, GGACT, LXN, THY1, SYNPO2, ACMSD and COLEC11 showed no survival or recurrence associations from the tumor data, suggesting these as unique biomarkers from NAT." (PMID 37575948, 2023). "Using our dataset and another high-quality dataset, we identified proteins that showed clinical prognosis and recurrence associations, of which GGACT, LXN, THY1, SYNPO2, ACMSD and COLEC11 were unique biomarkers identified from NAT that could not be revealed using tumor-based analysis." (PMID 37575948, 2023).